EIF4E (eukaryotic translation initiation factor 4E)
Description:
Acts in the cytoplasm to initiate and regulate protein synthesis and is required in the nucleus for export of a subset of mRNAs from the nucleus to the cytoplasm which promotes processes such as RNA capping, processing and splicing. Component of the protein complex eIF4F, which is involved in the recognition of the mRNA cap, ATP-dependent unwinding of 5'-terminal secondary structure and recruitment of mRNA to the ribosome (By similarity). This protein recognizes and binds the 7-methylguanosine (m7G)-containing mRNA cap during an early step in the initiation of protein synthesis and facilitates ribosome binding by inducing the unwinding of the mRNAs secondary structures. Together with EIF4G1, antagonizes the scanning promoted by EIF1-EIF4G1 and is required for TISU translation, a process where the TISU element recognition makes scanning unnecessary. In addition to its role in translation initiation, also acts as a regulator of translation and stability in the cytoplasm. Component of the CYFIP1-EIF4E-FMR1 complex which binds to the mRNA cap and mediates translational repression: in the complex, EIF4E mediates the binding to the mRNA cap (By similarity). Component of a multiprotein complex that sequesters and represses translation of proneurogenic factors during neurogenesis (By similarity). In P-bodies, component of a complex that mediates the storage of translationally inactive mRNAs in the cytoplasm and prevents their degradation. May play an important role in spermatogenesis through translational regulation of stage-specific mRNAs during germ cell development (By similarity). As well as its roles in translation, also involved in mRNA nucleocytoplasmic transport (By similarity). Its role in mRNA export from the nucleus to the cytoplasm relies on its ability to bind the m7G cap of RNAs and on the presence of the 50-nucleotide EIF4E sensitivity element (4ESE) in the 3'UTR of sensitive transcripts (By similarity). Interaction with the 4ESE is mediated by LRPPRC which binds simultaneously to both EIF4E and the 4ESE, thereby acting as a platform for assembly for the RNA export complex (By similarity). EIF4E-dependent mRNA export is independent of ongoing protein or RNA synthesis and is also NFX1-independent but is XPO1-dependent with LRPPRC interacting with XPO1 to form an EIF4E-dependent mRNA export complex (By similarity). Alters the composition of the cytoplasmic face of the nuclear pore to promote RNA export by reducing RANBP2 expression, relocalizing nucleoporin NUP214 and increasing expression of RANBP1 and RNA export factors DDX19 and GLE1 (By similarity). Promotes the nuclear export of cyclin CCND1 mRNA (By similarity). Promotes the nuclear export of NOS2/iNOS mRNA. Promotes the nuclear export of MDM2 mRNA. Promotes the export of additional mRNAs, including others involved in the cell cycle (By similarity). In the nucleus, binds to capped splice factor-encoding mRNAs and stimulates their nuclear export to enhance splice factor production by increasing their cytoplasmic availability to the translation machinery (By similarity). May also regulate splicing through interaction with the spliceosome in an RNA and m7G cap-dependent manner (By similarity). Also binds to some pre-mRNAs and may play a role in their recruitment to the spliceosome (By similarity). Promotes steady-state capping of a subset of coding and non-coding RNAs by mediating nuclear export of capping machinery mRNAs including RNMT, RNGTT and RAMAC to enhance their translation (By similarity). Stimulates mRNA 3'-end processing by promoting the expression of several core cleavage complex factors required for mRNA cleavage and polyadenylation, and may also have a direct effect through its interaction with the CPSF3 cleavage enzyme (By similarity). Rescues cells from apoptosis by promoting activation of serine/threonine-protein kinase AKT1 through mRNA export of NBS1 which potentiates AKT1 phosphorylation and also through mRNA export of AKT1 effectors, allowing for increased production of these proteins (By similarity).
Synonyms: eIF-4E; EIF4EL1; EIF4F; EIF4E1; AUTS19; CBP
Tractability: Small molecule: a structure with a bound ligand is known; a high-quality ligand is known; it has a binding pocket of medium quality; it belongs to a druggable protein family. PROTAC: it is named in the literature on targeted protein degradation; ubiquitination databases record sites on it; its protein half-life has been measured; a small molecule that binds it is known.
Target class: Other nuclear protein
Gene: Protein-coding gene on chromosome 4 (98,878,761 to 98,929,150, reverse strand). Ensembl gene ENSG00000151247.
Subcellular location: Cytoplasm, P-body; Cytoplasm; Cytoplasm, Stress granule; Nucleus; Nucleus speckle; Nucleus, nuclear body
Subcellular location (Human Protein Atlas): Cytoplasmic bodies; Cytosol; Nucleoplasm
Pathways (Reactome):
Metabolism of proteins: Activation of the mRNA upon binding of the cap-binding complex and eIFs, and subsequent binding to 43S; GTP hydrolysis and joining of the 60S ribosomal subunit; L13a-mediated translational silencing of Ceruloplasmin expression; Ribosomal scanning and start codon recognition; Translation initiation complex formation
Metabolism of RNA: Deadenylation of mRNA; Transport of Mature mRNA Derived from an Intronless Transcript; Transport of the SLBP Dependant Mature mRNA; Transport of the SLBP independent Mature mRNA
Developmental Biology: M-decay: degradation of maternal mRNAs by maternally stored factors; Z-decay: degradation of maternal mRNAs by zygotically expressed factors
Disease: Dengue Virus Genome Translation and Replication
Immune System: ISG15 antiviral mechanism
Signal Transduction: mTORC1-mediated signalling
Gene Ontology:
Molecular function: DNA-binding transcription factor binding; enzyme binding; eukaryotic initiation factor 4G binding; mRNA cap binding; protein binding; RNA 7-methylguanosine cap binding; RNA binding; translation initiation factor activity; RNA cap binding
Biological process: G1/S transition of mitotic cell cycle; negative regulation of autophagy; positive regulation of mitotic cell cycle; regulation of translation; mRNA export from nucleus; negative regulation of translation; translational initiation; nuclear export; regulation of translation at postsynapse, modulating synaptic transmission
Cellular component: cytoplasm; cytoplasmic ribonucleoprotein granule; cytoplasmic stress granule; cytosol; eukaryotic translation initiation factor 4F complex; excitatory synapse; extracellular exosome; nuclear speck; nucleoplasm; nucleus; P-body; perinuclear region of cytoplasm; RISC complex; translation repressor complex; chromatoid body; glutamatergic synapse; nuclear body; postsynapse
Genetic constraint (gnomAD): Loss-of-function variants: 0 observed, 33.07 expected, observed/expected ratio (o/e) 0, 90% interval 0 to 0.09. The upper end of that interval is the gene's LOEUF score, 0.09, which puts it in group 1 of 6, group 1 being the genes least tolerant of losing a copy. Missense variants: 113 observed, 269.68 expected, observed/expected ratio (o/e) 0.42, 90% interval 0.36 to 0.49. Synonymous variants: 71 observed, 90 expected, observed/expected ratio (o/e) 0.79, 90% interval 0.65 to 0.96.
Homologues: Orthologues: macaque EIF4E (99% identical), guinea pig EIF4E (99% identical), dog EIF4E (98% identical), mouse Eif4e (98% identical), pig EIF4E (96% identical), rat Eif4e (96% identical), tropical clawed frog eif4e (88% identical), zebrafish eif4eb (84% identical), zebrafish eif4ea (83% identical), Drosophila melanogaster eIF4E1 (47% identical), Drosophila melanogaster eIF4E4 (44% identical), Drosophila melanogaster eIF4E7 (44% identical), and 7 more. Paralogues in human: EIF4E1B (64% identical), EIF4E2 (34% identical), EIF4E3 (27% identical).
Diseases named in the same sentence as EIF4E in open-access papers:
EIF4E is named in the same sentence as 188 diseases in open-access papers, as found by Europe PMC text mining. Sharing a sentence is not in itself a finding about the gene and the disease. The quoted sentences say what the papers report.
breast carcinoma (98 papers, 1998 to 2025). "Remarkably, elevated levels of eIF4E have been associated with poor overall survival in breast cancer patients." (PMID 37766871, 2023). "EIF4E activation is implicated in cancer growth, and the knockdown of eIF4E reduces breast cancer growth." (PMID 35626002, 2022). "Immunohistochemistry on 134 estrogen receptor (ER+) primary breast cancer samples confirmed that high eIF4E expression was significantly associated with increased ERα and FOXM1, and significantly associated with tamoxifen resistance." (PMID 32066877, 2020). "Our research has shown that KIT-mutant melanoma patients have increased levels of MNK1 and phospho-eIF4E, and in breast cancer increased levels of p-MNK1 were associated with high-grade ductal carcinoma in situ." (PMID 32517051, 2020). "Developing drugs to specifically target EIF4E or its downstream pathways could also provide new avenues for treating HER2‐negative breast cancer patients, particularly high‐risk groups as identified by our model." (PMID 40842081, 2025). "believed that the expression level of eIF4E was related to tumor recurrence, and eIF4E might increase the risk of recurrence of breast cancer." (PMID 37601696, 2023). "In addition, there are several studies investigated the association of EIF4E and human tumors such as lung cancer, colorectal cancer, breast cancer, and head and neck carcinoma." (PMID 34659334, 2021). "For example, eIF4E overexpression is frequently found in patients with colorectal cancer (CRC) or breast cancer (BC); eIF5A2 overexpression is obviously associated with the advanced stage of ovarian cancer; eIF3D increases cell cycle progression and motility in prostate cancer (PCa)." (PMID 34016142, 2021). "Consistent with this hypothesis, using Tissue Microarray sections of breast cancer samples, we confirmed that elevated eIF4E expression was significantly associated with ERα and FOXM1 protein expression as well as with tamoxifen resistance." (PMID 32066877, 2020). "Indeed, a strong association of eIF4E with an angiogenic profile was observed in these breast cancer patients." (PMID 17010208, 2006). "It has been noted that eIF4E overexpression is associated with tumor angiogenesis in breast cancer." (PMID 17010208, 2006). "The expression and activation of eukaryotic translation initiation factor 4E (eIF4E) is associated with cell transformation and tumor initiation, but the functional role and the mechanism whereby it drives immune cell infiltration in breast cancer (BRCA) remain uncertain." (PMID 34876062, 2021). "Future research should focus on validating these findings in larger clinical cohorts and exploring targeted therapies against m7G‐modified genes, in particular EIF4E, to further improve outcomes for this subset of breast cancer patients." (PMID 40842081, 2025). "SiRNAs targeting eIF4E inhibit tumor growth and stimulate the cytotoxic effects of cisplatin in human breast cancer in vitro and in vivo, suggesting that cisplatin treatment in combination with eIF4E-siRNA therapy would be more successful." (PMID 37631029, 2023). "Further, experimentally increasing expression of eIF4E in a weakly invasive breast cancer cell line strongly enhances invasive ability (Nasret al., 2013)." (PMID 38628976, 2023). "In breast cancer, eIF4E promotes the expression of FGF-2 by regulating its translation efficiency, thereby promoting the tumorigenicity and angiogenesis of breast cancer." (PMID 38001714, 2023). "As another eIF4E inhibitor, N-7 benzyl guanosine monophosphate tryptamine phosphonamidite prodrug (4Ei-1) upregulates gemcitabine chemosensitivity in lung and breast cancers by inhibiting the mRNA cap-binding ability of eIF4E and degrading the eIF4E protease." (PMID 37631029, 2023).
breast carcinoma (continued). "To more deeply evaluate the clinical impact of AGO2, EIF4E3 and EIF4E in breast cancer, we used the Kaplan–Meier plotter database to plot the DMFS (distant metastasis-free survival)-related Kaplan–Meier curves of AGO2, EIF4E3 and EIF4E." (PMID 37353728, 2023). "Together, our data suggested RMC-6272 triggers apoptosis in breast cancers through regulating 4EBP1/eIF4E and downstream protein levels of the key anti-apoptotic protein MCL1." (PMID 37264081, 2023). "Many studies have shown that eIF4E is highly expressed in various cancer types (breast cancer, colon cancer, bladder cancer, etc.), which enhances their metastasis and angiogenesis." (PMID 38001714, 2023). "They found that that postpartum breast cancer samples contained cancer cells that strongly expressed phosphorylated eIF4E (active form) and that tumor CD8+ T cells displayed markers of dysfunction." (PMID 36598557, 2023). "Studies reported that suppressing eIF4E significantly reduced the migratory and invasive potential of breast cancer cells and metastasis of the breast cancer cells in a mouse model." (PMID 36009568, 2022). "TGCA database was used to analyze the expression of miR-3189-3p, c-MYC, 4EPB1, and eIF4E in breast cancer." (PMID 35642054, 2022). "In breast cancer, elevated expression of eIF4E protein was correlated with aggressive tumor phenotypes; additionally, eIF4E has a significant role in driving the metastasis of breast cancer." (PMID 36009568, 2022). "Tamoxifen-resistant estrogen receptor (ER+) breast cancer has a strong positive relationship with increased MNK phosphorylation of eIF4E and rapamycin-resistant KRASG12D colorectal cancer activated the MNK/eIF4E pathways with overexpression of c-MYC." (PMID 35877722, 2022). "A case-matched and sex-matched transcriptome screening identified that eIF4E and eIF5 act as potential prognostic markers for male breast cancer." (PMID 36387239, 2022). "Studies have shown that the inhibition of eIF4G/eIF4E complex interaction by the translation initiation inhibitor 4EGI-1 leads to growth restriction in human melanoma and breast cancer cells." (PMID 36360287, 2022). "For example, 4EGI-1 inhibits the formation of the eIF4E–eIF4G complex in breast cancer stem cells and induces apoptosis in malignant pleural mesothelioma; presumably, 4EGI-1 also inhibits the nuclear functions of eIF4E, but this remains to be tested." (PMID 34944805, 2021). "eIF4E silencing also increases Bax/Bcl-2 ratio and sensitizes breast cancer to cisplatin, adriamycin, paclitaxel and docetaxel." (PMID 33038921, 2020). "eIF4E was upregulated in breast cancer, colon cancer, head and neck cancer, non-Hodgkin’s lymphoma, and ovarian carcinoma, and was associated with the increasing grade of a disease." (PMID 32498447, 2020). "For example, in ER+ breast cancer tumors, the phosphorylation of eIF4E on Ser209 promotes tamoxifen-resistance through enhanced translation of RUNX2." (PMID 32517051, 2020). "Reports have shown that eIF4E is overexpressed in different types of cancers, including breast cancer." (PMID 32066877, 2020). "The genetic silencing of eIF4E, or pharmacologic inhibition using ribavirin, reduces the growth, invasion and metastasis of breast cancer." (PMID 33038921, 2020). "The activation of the MNK/eIF4E/β-catenin axis is involved in breast cancer cell response to chemotherapy." (PMID 32340135, 2020). "High expression of eIF4E appears to play an important role in breast cancer development and is correlated with breast cancer metastases." (PMID 31671902, 2019). "For instance, ribavirin, an antiviral guanosine analogue that competes with 5′-cap and inhibits eIF4E activity, inhibits the proliferation and clonogenic potential of breast cancer cell lines with elevated eIF4E levels." (PMID 31671902, 2019). "In breast cancer, high levels of eIF4E and phosphorylation of 4E-BP1 and S6 are correlated with worse survival." (PMID 29739984, 2018).
breast carcinoma (continued). "The goal of the study was to identify the effects of eIF4E reduction in tamoxifen-resistant breast cancer cells compared to a normal control." (PMID 30409155, 2018). "Both overexpression of eIF4E S209D and chemotherapeutic drugs activate Wnt/β-catenin by increasing β-catenin activity and Wnt/β-catenin-mediated transcription in breast cancer cells." (PMID 27926520, 2017). "Altogether, these results indicate that the collaborative activity of cIAP1 and CHIP is crucial in determining the levels of eIF4E and the related tumorigenic phenotype in breast cancer cell lines." (PMID 28852129, 2017). "In this study, we examined the phosphorylation level of eIF4E in breast cancer patients (stage IV) before and after chemotherapy, and assessed the role of eIF4E phosphorylation in the development of chemoresistance." (PMID 27926520, 2017). "Our data provide another mechanism by which CHIP plays a role in the suppression of breast cancer progression via regulation of eIF4E." (PMID 28852129, 2017). "Overexpression of eIF4E S209D facilitates breast cancer cell growth and depletion of eIF4E augments the anti-proliferative and pro-apoptotic effects of chemotherapeutic drugs." (PMID 27926520, 2017). "Collectively, our data indicate that MNK inhibition enhances the inhibitory effects of chemotherapeutic drugs in breast cancer cells, most likely by enhancing eIF4E phosphorylation and β-catenin activation." (PMID 27926520, 2017). "To further understand the role of eIF4E in breast cancer cells in response to chemotherapeutic drugs, we analyzed the proliferation and apoptosis in eIF4E-depleted cells upon chemotherapeutic drugs treatment." (PMID 27926520, 2017). "We showed that eIF4E is highly phosphorylated at serine 209 in breast cancer patients in response to chemotherapy, which significantly correlated with poorer clinical responses and outcomes." (PMID 27926520, 2017). "Depletion of eIF4E enhanced the anti-proliferative and pro-apoptotic effects of chemotherapeutic drugs in breast cancer cells." (PMID 27926520, 2017). "Consistent with the patient data, western blot analysis showed that doxorubicin, cyclophosphamide and fluorouracil time-dependently increased eIF4E phosphorylation at Ser209 in several breast cancer cell lines, including MCF-7, MDA-MB-231, SKBR-3 cells." (PMID 27926520, 2017). "We found that CGP57380 decreased eIF4E phosphorylation induced by chemotherapeutic drugs in breast cancer cells." (PMID 27926520, 2017). "SEMA3A inhibits cell adhesion and migration through an increase in integrin-α2β1 levels and through the promotion of RhoA translation via a mechanism that involves eIF4E in breast cancer models." (PMID 26755661, 2016). "Silencing of EIF4E was found to slow proliferation and arrest the cell cycle in G0/G1 phase in larynx, stomach, and breast cancer cells." (PMID 25943993, 2015). "Recently, we demonstrated that these NRs inhibit the growth of triple negative, estrogen receptor alpha (ER-α) and Her2-overexpressing breast cancer cells by blocking MNK initiated eIF4E activation." (PMID 25605250, 2015). "Significantly, unlike the Mnk inhibitors (CGP57380 and cercosporamide) and two clinically relevant retinoids (ATRA and 4-HPR), RRs show potent breast cancer cell growth inhibition and down-regulation of p-eIF4E." (PMID 24504069, 2014). "Together our findings provide the first preclinical proof-of-concept of novel Mnk degrading agents for Mnk/eIF4E based therapeutic treatment of breast cancers." (PMID 24504069, 2014). "In conclusion, the data provided in this manuscript show that RRs degrade Mnkl and block eIF4E phosphorylation to possibly promote cell death and inhibit cell growth survival and invasion in breast cancer cells." (PMID 24504069, 2014).